CIITA (class II major histocompatibility complex transactivator)
Diseases named in the same sentence as CIITA in open-access papers (continued):
Sharing a sentence is not in itself a finding about the gene and the disease.
tumor (continued). "Cumulatively, these findings demonstrated the that the expression of MHC class II molecules driven by CIITA in tumor cells was key in triggering an adaptive and protective immunity." (PMID 31417570, 2019). "In contrast a rapid infiltration of CD4+ T cells, followed by DC and CD8+ T cells was observed at the tumor site when mice were injected with CIITA-tumors." (PMID 31417570, 2019). "By genetically modifying tumor cells of distinct histological origin with the MHC-II transactivator CIITA, the physiological controller of MHC-II gene expression discovered in our laboratory, stable expression of all MHC class II genes was obtained." (PMID 31417570, 2019). "Syngeneic T/SA tumour cells were used for this, which were infected with FP recombinants that expressed CIITA-induced MHC-II molecules, for better presentation of the relevant viral protein peptides to the CD4+ T cells." (PMID 29385169, 2018). "Previous studies showed that epigenetic modifications contribute to transcriptional silencing of CIITA in human tumor cells." (PMID 25815463, 2015). "The coordinate regulation of HLA class II (HLA-II) is controlled by the class II transactivator, CIITA, and is crucial for the development of anti-tumor immunity." (PMID 24475282, 2014). "A more recent study demonstrated that silencing one of the four CIITA promoters, the CIITApIV, which is inducible by IFN-γ, causes the loss of MHC class II expression on tumor cells." (PMID 25071778, 2014). "Together, these data add mechanistic insight to prior observations of increased EZH2 expression and decreased CIITA expression in multiple tumor types." (PMID 22563434, 2012). "We have shown recently that inhibition of RAB27A expression by stable transfection with shRNA in a human tumor cell line, HeLa-CIITA (a modified HeLa cell line expressing the MHC class II machinery), induces around 70% decrease in exosome secretion." (PMID 24009879, 2012). "As a different approach to obtain optimal triggering of the adaptive anti-tumor immune response, a vaccination strategy with tumor cells transduced with the AIR-1-encoded MHC-II transactivator CIITA has been explored in our laboratory." (PMID 22849661, 2012). "In contrast the site of CIITA-transfected tumor cells injection was rapidly infiltrated by CD4+ T cells." (PMID 22849661, 2012). "That CIITA-dependent MHC class II expression in tumor cells was instrumental to trigger a protective immune response against the parental tumor was also demonstrated by vaccination experiments with non replicating CIITA-transfected tumor cells." (PMID 22849661, 2012). "Expression of MHC II is regulated primarily at the level of transcription by the Class II Transactivator, CIITA, and decreased CIITA expression is observed in multiple tumor types." (PMID 22563434, 2012). "Therapeutically, strategies aiming to restore or enhance MHC‐II expression—such as IFN‐γ administration, CIITA overexpression, or epigenetic reactivation—show promise for augmenting T cell‐mediated tumour recognition and broadening the therapeutic scope beyond MHC‐I‐restricted approaches." (PMID 40673641, 2025). "In contrast, epigenetic silencing of key transcriptional regulators such as NLRC5 (for MHC‐I) and CIITA (for MHC‐II) appears more common across a broader range of tumours and may be pharmacologically reversible." (PMID 40673641, 2025). "Expression of MHC-II genes including HLA genes, CIITA, and CD74 were associated with an anti-tumor T cell response, represented by positive correlation with proportion of infiltrating CD8 + T cells, and negative correlation with infiltration of immunosuppressive T regs." (PMID 40361136, 2025). "In addition, the association between CIITA gene mutations and carcinogenesis underscores the importance of maintaining proper CIITA function in the tumor microenvironment 26,27." (PMID 40861816, 2025).
tumor (continued). "Interestingly, the Ad‐CIITA mutant also led to robust tumor cell killing in the presence of PBMCs (78.3% ± 21.7), despite the lack of MHC‐II expression." (PMID 39535369, 2025). "Tumoral CIITA/MHC-II silencing is responsible for RCOR2-induced tumor immune evasion." (PMID 40608411, 2025). "Of note, CIITA-OSCC vaccinated animals that reject the tumor develop an anti-tumor immunological memory capable of rejecting or strongly counteracting challenges with parental OSCC tumor cells." (PMID 39035008, 2024). "Interestingly, ex vivo analysis of MOC2-CIITA tumor growing in vivo showed a clear reduction of MHC-II expression, thus strongly correlating anti-tumor capacity to respond in vivo to the amount of CIITA-dependent MHC-II expression." (PMID 39035008, 2024). "pDCs from tumor-bearing mouse brain, blood, lymph node (LN), and bone marrow (BM) one-week post-intracranial tumor implantation were analyzed for the presence of activating markers (MHC-II and CIITA) and compared between tumor-bearing (red) and normal (black) mice." (PMID 39456552, 2024). "Additionally, Nutlin-3 can act as an immune adjuvant by inducing the expression of HLA-I and HLA-DR in tumors through the CIITA, thereby augmenting the anti-tumor properties of T cells." (PMID 39223632, 2024). "Furthermore, IHC analysis revealed an up-regulation of immune-related factors HLA-DPA1 and CIITA in tumor tissues overexpressing AEG-1." (PMID 39483471, 2024). "Studies with DNA methyltransferase (DNMT) inhibitors such as 5-azacytidine (5-AZA), plus HDAC inhibitors such as Trichostatin A (TSA), established that epigenetic mechanisms silence CIITA-PIV in tumor cells, and that interference with such mechanisms restores CIITA expression." (PMID 38915093, 2024). "This is a crucial element for the construction of a future vaccine against GBM, particularly because we have already identified many new and potential GBM-specific tumor antigens in our recent studies on the characterization of the MHC-II immunopeptidome of human GBM cells transduced with CIITA." (PMID 36993983, 2023). "In recent years, CIITA has been speculated to be an important exploration target in anti-checkpoint blockade immunotherapy and anti-tumor vaccination." (PMID 37927478, 2023). "In this we were motivated by early results showing the human tumor cell lines expressing MHC-II molecules after transfection with CIITA could process and present peptides from M. Tuberculosis Ag85 protein to antigen-specific CD4+ T cell clones." (PMID 37467968, 2023). "Epigenetic mechanisms of CIITA silencing, particularly in tumor cells, may represent a way to avoid tumor antigen recognition by the immune system and thus elusion from anti-tumor immune response." (PMID 37467968, 2023). "Because these primary tumors contain immune infiltrates, the increased CIITA expression could result from CIITA expression in either tumor cells or immune cells." (PMID 35225231, 2022). "Similarly, CIITA-expressing DFT cells have the potential to present MHC-II-restricted tumour antigens to CD4+ T cells and potentiate anti-DFT immune responses." (PMID 36259237, 2022). "Evidence for inducibility of MHC-II expression in DFT cells suggests that MHC-II-restricted tumour antigen presentation could occur in the physiological setting under inflammatory conditions that upregulate CIITA." (PMID 36259237, 2022). "CIITA-expressing GBM cells express very high levels of HLA-II complexes and naturally present a large repertoire of known HLA-I ligands, but most importantly, of novel HLA-II ligands derived from shared and immunogenic tumor-associated antigens (TAAs)." (PMID 33592498, 2021). "This hypothesis is supported by previous functional demonstration that other human tumor cell lines rendered HLA-II positive by transfection with CIITA process and present in vitro exogenously derived peptides." (PMID 33592498, 2021).
tumor (continued). "In addition, a heterogeneous, but also a distinct expression pattern of CIITA was found between lymphocytes and tumor cells." (PMID 34359808, 2021). "It has been reported before that CIITA-transfected tumor cells gained ability to prime in vivo naïve CD4+ cells, and thus, they may serve as APCs." (PMID 33592498, 2021). "Roberto S. Accolla and colleagues revealed that immune cells including CD4+ T cells, CD8+ T cells, dendritic cells and macrophages would be rapidly infiltrated into tumor cells that were stably transfected with CIITA and had expression of MHC class II molecules." (PMID 34040608, 2021). "The critical role of CIITA in immune response to tumor cells was well established in literature." (PMID 34404901, 2021). "These tumors present frequent genomic alterations in CIITA, comprising structural genomic rearrangements, missense, nonsense, and frameshift mutations found in 53% of primary tumor biopsies and PMBCL-derived cell lines." (PMID 33499042, 2021). "Furthermore, gene transfer of CIITA into tumor cells resulted in a stimulation of tumor specific CD4+ T cells in vivo associated with a long-lasting protective immunity, as well as an increased repertoire of tumor-associated HLA class II antigens." (PMID 34359808, 2021). "We confirmed that TAAs can be presented in the three CIITA-expressing GBM cell lines, and in total, 138 HLA-I peptides derived from known GBM-associated tumor antigens could be identified." (PMID 33592498, 2021). "In line with this, we showed that tumor cells and the decellularized matrix modulate the expression of CIITA in differentiated macrophages, corroborated by the in vivo correlate demonstrating reduced expression of CIITA in tumor-infiltrating macrophages." (PMID 34680345, 2021). "Single-cell cytotoxicity assays of cytotoxic CD4+ T cells specific for tumor antigen (NY-ESO-1 and MAGE-A3), which were isolated using MHC class II tetramers, demonstrated their direct killing of tumor cells pre-treated with IFN-γ or stably transduced with CIITA to enhance MHC class II expression." (PMID 34910940, 2021). "Interestingly, it was found that CIITA-tumor tissue was rapidly infiltrated by CD4+ T cells already at day 4 after tumor cell injection." (PMID 33138029, 2020). "For example, could a specific correlate of protection be shown in vivo in the tumor tissue and, importantly, could CIITA-tumor cells function as APC to directly prime tumor–specific virgin CD4+ Th cells in vivo?" (PMID 33138029, 2020). "Thus, it was important to establish the relative contribution of distinct cellular subpopulation to the in vivo protection against CIITA-driven MHC-II expressing tumor cells in our model." (PMID 33138029, 2020). "The induction could be carried out by transfecting the tumor cells with the Class II, major histocompatibility complex, transactivator (CIITA) loaded vaccine." (PMID 32911646, 2020). "In previous publications, we have extensively reviewed our approach aimed at rendering tumor cells constitutively positive for MHC class II expression by the genetic transfer of the MHC class II transactivator discovered in our laboratory, also designated CIITA." (PMID 33138029, 2020). "Therefore, by vaccinating the tumor cells with this CIITA loaded vaccine, the tumor cells would express MHC Class II." (PMID 32911646, 2020). "Interestingly the CIITA-tumor microenvironment was characterized by extensive areas of tumor cell necrosis." (PMID 31417570, 2019). "The final demonstration that CIITA-mediated MHC-II expressing tumor cells could indeed function as classical APC came recently by using a transgenic mouse model, in which professional APC can be transiently deleted." (PMID 31417570, 2019). "Ectopic expression of CIITA in MHC-II–negative tumour cells can render these cells MHC-II–positive." (PMID 29385169, 2018).
tumor (continued). "Thus, similarly to the preventive vaccination approach with CIITA-expressing tumor cells, the protective anti-tumor immune response generated by the treatment with L19mTNFα was associated to a rapid appearance and conversion toward a TH1 immune phenotype." (PMID 24600588, 2014). "Indeed, the histological picture observed in the tumor microenvironment generated by CIITA-transfected tumor cells was the classical picture of an inflammatory lesion." (PMID 24600588, 2014). "Importantly, CIITA-tumor vaccinated mice develop an anamnestic response allowing them to reject parental tumors very efficiently." (PMID 22849661, 2012). "Moreover, functional enrichment analyses suggest that CIITA may influence tumor-immune interactions by modulating immune response pathways." (PMID 40861816, 2025). "A combination of existing immunotherapeutic approaches, such as immune-checkpoint inhibitors or oncolytic viruses, with MHC-II expression transcriptionally enhanced by CIITA in cancer cells could potentially increase the recognition of tumor antigen and effector T-cell activation." (PMID 40141198, 2025). "Although the overall frequency of CIITA mutations remained relatively low, these alterations may nonetheless exert substantial influence on tumor initiation and progression." (PMID 40861816, 2025). "Next, we studied whether CIITA silencing regulates RCOR2-induced tumor immune evasion." (PMID 40608411, 2025). "Additionally, promoting MHC-II expression mediated by CIITA in tumor cells may serve as a novel immunotherapeutic approach, although further research is needed to validate this possibility." (PMID 39223632, 2024). "Next, we examined whether CIITA is responsible for tumor alleviation mediated by B7-H3 inhibition." (PMID 36869048, 2023). "To further characterize the CIITA-mediated anti-tumoral response, we verified whether vaccination with CIITA-positive tumor cells in one brain hemisphere could prevent the growth of parental tumor cells in the opposite hemisphere." (PMID 36993983, 2023). "The results presented here may help to define a more precise immunological signature of patients affected by CRC, highlighting the role of the tumor microenvironment and extending our knowledge of different immunological signatures involving alterations in complexes driven by CIITA and B2M." (PMID 37046620, 2023). "Furthermore, our results strongly suggest that CIITA-induced MHC class II cell surface molecules in GL261-CIITA tumor cells are the key element in triggering the adaptive CD4+ Th cell anti-tumor response, most likely serving as antigen-presenting molecules for tumor-specific GBM peptide antigens." (PMID 36993983, 2023). "CIITA is a non-DNA-binding coactivator of major histocompatibility complex (MHC) class II molecules whose high expression is usually associated with enhanced involvement of CD4+ lymphocytes in tumor suppression and a better prognosis." (PMID 35425715, 2022). "We have shown before that stable expression of CIITA in human tumor cells leads to constitutive functional expression of HLA-II, that endogenous proteins can also be directed to presentation on HLA-II complexes, and that HLA-II expressing cells may directly engage and activate CD4+ TH cells." (PMID 33592498, 2021). "Furthermore, loss-of-function mutations in CIITA resulted in the lack of HLA class II expression, which was found in various tumor types, while a substitution of A to G in the 5′ flanking region of the CIITA promoter was associated with a higher expression." (PMID 34359808, 2021). "Therefore, it was tempting to investigate whether the forced expression of CIITA into tumor cells could render these cells more “visible” and, thus, immunogenic for tumor specific CD4+ Th cells." (PMID 33138029, 2020).
tumor (continued). "Our approach is to render tumor cells surrogate antigen presenting cells for their own tumor antigen by forcing them to express de novo MHC class II molecules after the genetic transfer of CIITA, the major transcriptional controller of MHC class II gene expression." (PMID 33138029, 2020). "Thus, both of B2M and CIITA contributed to the incapability of forming tumor-like mass." (PMID 32746912, 2020). "Additionally, tumor-draining lymph nodes of mice vaccinated with CIITA-tumor cells showed a more polarized TH1-type phenotype with respect to a rather polarized TH2-type phenotype observed in similar lymph nodes of mice injected with parental tumor cells." (PMID 31417570, 2019). "Thus, forcing the “physiological” expression of MHC-II molecules by transfecting CIITA into tumor cells resulted in a dramatic modification of the tumor microenvironment which was associated to specific tumor rejection and/or strong retardation of tumor growth." (PMID 31417570, 2019). "Indeed, we could demonstrate that CIITA-transfected tumor cells of distinct histological origin can be efficiently rejected or strongly retarded in their growth when injected into immunocompetent syngeneic mice." (PMID 31417570, 2019). "When experiments were performed to stably express CIITA in both human and mouse tumor cells, we could demonstrate the constitutive expression of MHC-II genes and corresponding molecules and, importantly, the acquisition of antigen processing and presentation to primed TH cells." (PMID 31417570, 2019). "Alternatively, preformed MHC-II–TAA peptide complexes derived from CIITA-transfected tumor cells could be shed from the cells, captured by professional APC and used by these cells to reach the AAA necessary to trigger an efficient priming of tumor-specific CD4+ TH cells." (PMID 24600588, 2014). "Indeed, it was possible to show that CIITA-transduced tumor cells of at least four distinct histological origin can be efficiently rejected or strongly prevented in their growth when injected into immunocompetent syngeneic mice, demonstrating the general applicability of our model system." (PMID 24600588, 2014). "Many tumor cells including leukemias, lymphomas, and carcinomas, avoid immune recognition due to a dysfunctional antigen presentation pathway, largely caused by epigenetic silencing (e.g., histone deacetylation or DNA methylation) of MHC2TA, the gene encoding CIITA." (PMID 24062768, 2013). "The comparative study of the tumor microenvironment and of tumor draining lymph nodes in mice injected with parental or with CIITA-transfected tumor cells provided critical insight on the mechanisms triggered by CIITA-transfected tumor cells and their possible role as surrogate APCs." (PMID 22849661, 2012). "A study demonstrated that CIITA serves as a master regulator of MHC class II expression and is critical for the induction of tumor immunogenicity through enhanced CD4+ T cell activation." (PMID 40861816, 2025). "IFN-γ interacts directly with tumor cells via the IFN-γ receptor, leading to CIITA expression, which has been shown to be required for treatment efficacy in an MHC-II-independent manner." (PMID 41312368, 2025). "In tumor cells, silencing MAP1LC3C inhibits CIITA expression and suppresses HLA class II production." (PMID 39928678, 2025). "Hypoxic conditions in tumours can suppress forkhead box O1 (FoxO1) activity, impairing its binding to the CIITA promoter and reducing MHC‐II transcription, consequently promoting immune evasion and tumour progression." (PMID 40673641, 2025). "The RCOR2/LSD1 sub-axis suppresses RNF43 transcription to activate Wnt/β-catenin signaling in tumor cells, whereas the RCOR2/HDAC1/2 sub-axis inhibits CIITA and MHC-II expression in tumor cells to block activation of CD4+ and CD8+ T cells." (PMID 40608411, 2025).